HEXIM2-AS2 (HEXIM2 antisense RNA 2)
Synonyms: HSAL3; RP13-890H12.2
Gene: Long non-coding RNA gene on chromosome 17 (45,168,800 to 45,176,108, reverse strand). Ensembl gene ENSG00000267288.
Diseases named in the same sentence as HEXIM2-AS2 in open-access papers:
HEXIM2-AS2 is named in the same sentence as 1 disease in open-access papers, as found by Europe PMC text mining. Sharing a sentence is not in itself a finding about the gene and the disease.
HEXIM2-AS2 shares sentences with these, for which no sentence is quoted: hepatocellular carcinoma (1 paper).